UBE2L3 (ubiquitin conjugating enzyme E2 L3)
Diseases named in the same sentence as UBE2L3 in open-access papers (continued):
Sharing a sentence is not in itself a finding about the gene and the disease.
tumor (continued). "Furthermore, it has been observed that UBE2L3 exhibits abnormally high expression in various human tumor types, indicating a potential role for UBE2L3 as an oncogene." (PMID 38656363, 2024). "Additionally, overexpression of CUL1 or UBE2L3 decreases E7 protein levels and suppresses in vivo tumor growth." (PMID 38226814, 2024). "High expression of UBE2L3 was correlated with advanced tumor stage and adverse outcomes." (PMID 29137415, 2017). "Altogether, knockdown of UBE2L3 inhibited in vivo tumor growth of NSCLC cells." (PMID 29137415, 2017). "Mechanistically, UBE2L3 downregulation led to increased tuberous sclerosis complex 2 (TSC2) expression, suppressing mTOR activity and altering autophagic processes in tumor cells." (PMID 41943836, 2026). "UBE2L3, an E2 ubiquitin-conjugating enzyme, has been shown to reduce HPV16 E7 protein levels and inhibit tumor growth in HPV+ HNC cells through its overexpression." (PMID 40990020, 2025). "Conversely, overexpression of CUL1 and UBE2L3 in HPV+ HNC cells decreases HPV16 E7 protein levels and suppresses tumor growth in vivo." (PMID 38226814, 2024). "Conversely, the overexpression of CUL1 and UBE2L3 in HPV+ HNC cells decreases HPV16 E7 protein levels and suppresses tumor growth in vivo." (PMID 38226814, 2024). "Our results suggest that Cul1 or Ube2l3 overexpression results in HPV16 E7 protein degradation and tumor suppression." (PMID 38226814, 2024). "Hsa-miR-1261, upstream of UBE2L3, was downregulated in HCC; its role in tumorigenesis has been reported in several different tumor types." (PMID 31886256, 2019). "Here, we reported that UBE2L3, a member of the ubiquitin-conjugating enzymes (E2s), were overexpressed in non-small-cell lung cancer (NSCLC) tissues compared with the non-tumor tissues." (PMID 29137415, 2017). "To assess UBE2L3 expression in NSCLC, we first examined UBE2L3 level in 28 cases of NSCLC and matched non-tumor tissues by qRT-PCR and IB." (PMID 29137415, 2017). "Additionally, PTTG1 may correlate with the BLCA tumor microenvironment and exert transcriptional activity by targeting CHEK2, OCIAD2, UBE2L3, and ZNF367 in BLCA tissue." (PMID 35768832, 2022). "Finally, UBE2L3 was screened out and its ceRNA regulatory network was constructed; the expression levels of molecules in this regulatory network were also confirmed by qPCR in tumor tissues and adjacent nontumor tissues." (PMID 31886256, 2019). "UBE2L3 was upregulated in HCC and showed a significant positive correlation with tumor stage and negative correlations with OS and DFS." (PMID 31886256, 2019). "In our study, hsa_circ_0009910 and UBE2L3 were confirmed to be highly expressed and miR-1261 was expressed at a low level by qPCR in 30 pairs of samples from HCC patients, including tumor tissues and adjacent nontumor tissues." (PMID 31886256, 2019).
cancer (10 papers, 2017 to 2024). A tumor composed of atypical neoplastic, often pleomorphic cells that invade other tissues. "The role of UBE2L3 in the initiation and progression of various cancers has been well documented, but its specific significance in GC is not yet fully elucidated." (PMID 38656363, 2024). "UBE2L3 controls the protein stability of several signaling molecules, which acts on cancer regulation." (PMID 35265070, 2022). "The data presented in this study provide insight into the high expression of UBE2L3 in various human cancers, suggesting that UBE2L3 may be involved in the pathogenesis of malignant tumors." (PMID 38656363, 2024). "Then we used EdU to detected cell proliferation and found that repressed UBE2L3 could weaken the proliferation capacity of cancer cells." (PMID 33726770, 2021). "Given that UBE2L3 primarily functions in cancer initiation via accelerating p27kip1 degradation, we then asked whether the combination of UBE2L3 and p27kip1 could better predict survival than either protein." (PMID 29137415, 2017). "Similarly, OCIAD2, UBE2L3, and ZNF367 also displayed intimate association with cancer development." (PMID 35768832, 2022). "Hence, UBE2L3 might be a potential therapeutic target to treat cancers that are characterized by elevated UBE2L3 expression." (PMID 32203172, 2020). "MARCHF8 knockout restores CUL1 and UBE2L3 expression, decreasing E7 protein levels and inhibiting the proliferation of HPV-positive cancer cells." (PMID 38226814, 2024). "Consequently, overexpressed UBE2L3 was detected in different tissues and cell lines of NSCLC, and its expression level has been directly related to the cancer stage in patients." (PMID 37762133, 2023). "Silencing LINC01116 could inhibit the growth of cancer cells, as well as EMT process, by regulating miR-744-5p/ubiquitin conjugating enzyme E2 L3 (UBE2L3) axis." (PMID 33726770, 2021). "And based on qRT-PCR results, after overexpressing miR-744-5p, the expression level of UBE2L3 was inhibited in cancer cells but no significant changes were presented in LRP3 and NFIX expression." (PMID 33726770, 2021). "UBE2L3 has 18 lysine residues, 14 of which were previously identified as ubiquitylated based on di-Gly modifications detected in proteomic analyses of non-phagocytic cells and cancer cell lines." (PMID 28147281, 2017).
bacterial infection (1 paper, 2017). "UBE2L3 depletion by caspase-1 occurs in macrophages and dendritic cells after canonical and non-canonical inflammasome activation by microbial or sterile signals and bacterial infection." (PMID 28147281, 2017). "Caspase-1, but not caspase-4, controls pyroptosis- and ubiquitin-independent proteasomal degradation of UBE2L3 upon canonical and non-canonical inflammasome activation by sterile danger signals and bacterial infection." (PMID 28147281, 2017).
head and neck tumor (1 paper, 2024). "On the contrast, overexpression of UBE2L3 decreases E7 protein levels and suppresses head and neck tumor growth in vivo." (PMID 38795139, 2024).
infection (1 paper, 2017). The state of being infected such as from the introduction of a foreign agent such as serum, vaccine, antigenic substance or organism. "Taken together, during priming or natural infection with Gram (+ve) or Gram (−ve) pathogenic or commensal bacteria, the UBE2L3 status of host cells sets the upper limit on the amount of pro-IL-1β substrate available for caspase-1 processing and thus controls mature IL-1β production." (PMID 28147281, 2017). "IL-1β production at 18 hr post-infection with all three bacteria was markedly reduced in cells overexpressing UBE2L3 and significantly increased in cells in which UBE2L3 expression was silenced." (PMID 28147281, 2017).
infectious disease (1 paper, 2022). A disorder directly resulting from the presence and activity of a microbial, viral, or parasitic agent in humans. "Genetic studies showing an association between UBE2L3 and autoimmune and infectious diseases." (PMID 35265070, 2022).
inflammation (1 paper, 2020). Aberrant reaction of the microcirculation characterized by movement of fluid and leukocytes from the blood into extravascular tissues. "This is the first depiction of the expression of UBD, UBE2L3, CUL2, and HSP5 genes in the colonic mucosa from patients with UC, suggesting that these genes could be involved in the pathogenesis of colonic inflammation in patients with UC." (PMID 32410873, 2020).
intestinal disorder (1 paper, 2024). A non-neoplastic or neoplastic disorder that affects the small or large intestine. "In two GWAS, it was discovered that UBE2L3 may be a novel IBD risk gene that is crucial to the pathogenesis of intestinal disorders." (PMID 38348734, 2024).
psychiatric disorder (1 paper, 2021). A disorder characterized by behavioral and/or psychological abnormalities, often accompanied by physical symptoms. "Dysregulation of UBE2L3 expression in the blood may represent the activity in the brain, which may involve the pathogenesis of psychiatric disorders, including PTSD and MDD." (PMID 34630024, 2021).
UBE2L3 also shares sentences with these, for which no sentence is quoted: rheumatoid arthritis (4 papers); celiac disease (2); Hashimoto thyroiditis (2); hepatitis B virus infection (2); oral cancer (2); viral infection (2); allergic disease (1); alopecia areata (1); Autoimmunity (1); dyslipidemia (1); Graves disease (1); head and neck cancer (1); immune diseases (1); inflammatory bowel disease (1); Insulin resistance (1); Intellectual disability (1); juvenile idiopathic arthritis (1); metabolic disease (1); multiple myeloma (1); neuroblastoma (1); neutrophilic disease (1); oral squamous cell carcinoma (1); ovarian carcinoma (1); triple-negative breast carcinoma (1); ulcerative colitis (1).